MTSS1 (MTSS I-BAR domain containing 1)
Diseases named in the same sentence as MTSS1 in open-access papers (continued):
Sharing a sentence is not in itself a finding about the gene and the disease.
tumor (continued). "Among the targets of Arid4a, MTSS1, RB1, and PTEN are involved in the suppression of tumor cell metastasis, while TIMP2 is believed to be a suppressor of tumor angiogenesis." (PMID 40066676, 2025). "(2021) reported that circ‐102,166 sponge the miR‐182 expression by acting as a tumor suppressor, and reduces the cell growth, migration, invasion, and tumorigenicity of HCC by upregulating the miR‐182 targets’ MTSS1 and FOXO3a." (PMID 39617640, 2024). "MTSS1 and CMTM5 are tumor suppressor genes, although in some cancer types, MTSS1 was identified as a tumor enhancer." (PMID 34390367, 2021). "Meanwhile, miR-182 inhibits BRCA1, a tumor suppressor involved in DNA repair, and MTSS1, a metastasis suppressor, and upregulates the EMT promoter HMGA2, thus increasing EOC cell invasiveness in vitro and tumor metastasis in vivo." (PMID 32993038, 2020). "Generally, miR-182-5p regulates the apoptosis of tumor cells by targeting certain special genes, such as FOXO1, MTSS1, HMGA2, CASP9, and FOXO3, and these target genes were also predicted by our experiment." (PMID 32090086, 2020). "The mRNAs HOXA5, MTSS1, PTEN, and RECK are reported to have important tumor-suppressive roles in OC, though their role in HGSC is not specifically shown." (PMID 31842477, 2019). "Down-regulated MTSS1 and up-regulated LIMA1 were key factors stabilizing the cytoskeleton of tumor cells under μg conditions." (PMID 31261642, 2019). "Relative gene expression was evaluated and tumor samples were then spatially distributed according to the expression of the trios of genes: PRSS11, MTSS1, CLPTM1 and PRSS11, MTSS1, SMYD2." (PMID 18601734, 2008). "Some studies have shown that MTSS1 is also reduced in non-metastatic tumor cell lines and samples while being overexpressed in tumors compared with normal tissue." (PMID 39625546, 2024). "MTSS1 has attracted much attention for its role as a tumor suppressor, being absent or expressed at reduced levels in advanced and metastasizing cancers." (PMID 39625546, 2024). "MTSS1 is a putative tumor suppressor in a variety of cancers, not only limited to epithelial cancers." (PMID 37920825, 2023). "This study has not only experimentally validated the regulation of the expression of tumor-suppressive mRNAs such as HOXA5, MTSS1, PTEN, and RECK by MAGI2-AS3 in HGSC but also has suggested a network of how various pathways converge to aid in tumor suppression." (PMID 31842477, 2019). "This conclusion is oversimplified, as both Timp3 and Mtss1 do not always act as tumor suppressors in HCC." (PMID 29050362, 2017). "Several groups have shown that lack of MTSS1 promotes tumor growth through enhanced cell migration and invasion as well as enhanced cell proliferation." (PMID 25996952, 2015). "More importantly, ectopic expression of a non-degradable MTSS1 exerts stronger effects than WT-MTSS1 in suppressing tumor cell proliferation and migration." (PMID 24318128, 2013). "MTSS1 has been found to be transcriptionally expressed at lower levels or absent in a limited number of tumour cells." (PMID 21696600, 2011). "The mechanism for the down-regulation of MTSS1 to tumor progression, especially metastasis, is not clear." (PMID 20712855, 2010). "Tumor expression of PRSS11, MTSS1, CLPTM1 and SMYD2, was evaluated by real time PCR." (PMID 18601734, 2008). "Expression of PRSS11, MTSS1, CLPTM1 and SMYD2 was determined in tumor samples." (PMID 18601734, 2008). "Thus, we analyzed T cells in the H1975 tumor tissues with or without MTSS1 knockdown grafted in PBMC-humanized mice by immunohistochemistry staining and flow cytometry." (PMID 36810288, 2023). "This study for the first time highlights the tumor-suppressive role of LncRNA MAGI2-AS3 in HGSC and demonstrates its involvement in the regulation of miR-15b-5p, miR-374a-5p, and miR-374b-5p, and of their downstream mRNA targets (HOXA5, MTSS1, PTEN, and RECK) in HGSC cell lines." (PMID 31842477, 2019).
tumor (continued). "However, the strong positive expression rate of MTSS1 was not correlated with patient age, tumor differentiation or the presence of lymphatic metastasis (P>0.05)." (PMID 25295101, 2014). "No obvious staining of MTSS1 was observed in stromal cells in either normal or tumour tissues." (PMID 21696600, 2011). "Nevertheless, it is not known whether MTSS1 is involved in the regulation of tumor immunology." (PMID 36810288, 2023). "In another setting, perhaps MTSS1 loss would simply give cancer cells more of an advantage to disseminate from the primary tumor; however, in PDAC, where the CAF population is so massive, the loss of MTSS1 may not just aid in dissemination, but proliferation as well." (PMID 28146435, 2017). "With the Wilcoxon rank test we find genes such as MYC, CCNE1, KRAS, NDRG1, MLL4 and MTSS1 for which data set specific normal tissue expression may not be significantly different from all tumor samples but is variable between low and high copy number tumor samples." (PMID 22174824, 2011). "MTSS1 protein expression was tested with IHC in HCC and paired normal tissues (for some cases, there are tumor and adjacent normal tissue in the same slide)." (PMID 22681717, 2012).
cancer (48 papers, 2010 to 2025). A tumor composed of atypical neoplastic, often pleomorphic cells that invade other tissues. "The mechanisms underlying the anticancer functions of MTSS1 are not yet fully understood; however, several mechanisms have been identified in various types of cancer." (PMID 39625546, 2024). "The association of low MTSS1 expression with advanced cancer stages and metastasis highlights its significance as a prognostic marker for cancer progression." (PMID 39625546, 2024). "Here, we dissect the role of Missing-In-Metastasis (MIM), or Metastasis suppressor 1 (MTSS1), a cancer-associated membrane and actin cytoskeleton regulating protein, in B cell-mediated immunity by taking advantage of MIM knockout mouse strain." (PMID 32373113, 2020). "As MIM has been implicated in various cancers we further went on to analyse what mutations have been found in MTSS1 in different cancer samples using cBioPortal64,65." (PMID 30858428, 2019). "MTSS1 is highly expressed in some cancer types and its loss correlates with metastasis and poor prognosis, including breast cancer." (PMID 29497041, 2018). "Metastasis suppressor 1 (MTSS1) is an important tumor suppressor protein, and loss of MTSS1 expression has been observed in several types of human cancers." (PMID 24318128, 2013). "Thus, MTSS1 downregulation in cancer related to metastatic risk is more commonly observed than the few cases of MTSS1 upregulation related to metastasis." (PMID 39625546, 2024). "In analyses of several public clinical datasets of LUAD46–48, we found that MTSS1 mRNA and protein levels were significantly lower in cancer tissues as compared with normal adjacent tissues (NATs), and MTSS1 downregulation in LUAD was associated with poor patient survival." (PMID 36810288, 2023). "According to functional and mechanistic studies, the MTSS1 protein might be associated with the spread of cancer to various organ sites, most likely by interaction with the actin cytoskeleton, or by being regulated by miRNAs." (PMID 37635248, 2023). "Moreover, PDAC cells treated with cancer-associated fibroblast-conditioned media also have increased metastatic potential, which is augmented by loss of MTSS1." (PMID 28146435, 2017). "We suggest that the observed loss of Mtss1 in cancers may compromise junction stability and thus promote EMT and metastasis." (PMID 22479308, 2012). "Therefore, loss of MTSS1 in cancers may lead to the loss of junction stability, which ultimately promotes EMT and metastasis." (PMID 24318128, 2013). "The involvement of MTSS1 in the formation and traffic of intracellular vesicles has already found practical applications in experimental drug delivery in cancer treatment using magnetic nanoparticles." (PMID 39625546, 2024). "Knockout mouse experiments have provided further arguments for MTSS1’s role in cancer beyond the control of actin dynamics." (PMID 39625546, 2024). "The regulation of MTSS1 expression remains an open question, despite the frequently observed changes in MTSS1 expression levels in different tissues and different cancers and the role of MTSS1 expression levels in carcinogenesis." (PMID 39625546, 2024). "Metastasis suppressor 1 (MTSS1) has been reported to play important roles in suppressing cancer progression." (PMID 39519115, 2024). "Understanding the role of MTSS1 in cancer biology and the mechanism is crucial for employing it in therapeutic strategies." (PMID 39625546, 2024). "Four mRNAs, including MTSS1 mRNA, which is important for cancer development, were down-regulated in SNHG15-expressing cells." (PMID 39519115, 2024). "These recent studies indicate the versatile role of MTSS1 as a scaffold protein to regulate intrinsic malignant behaviors of cancer cells." (PMID 36810288, 2023). "Dysregulation of MTSS1 have been reported in numerous types of cancer, and down-regulation of MTSS1 is correlated poor survival rate 30,31." (PMID 38021156, 2023).
cancer (continued). "In metastatic cells, MTSS1 expression is typically diminished, whereas its relative expression is unclear in primary cancers." (PMID 37635248, 2023). "T cell-mediated killing of cancer cells was also suppressed by MTSS1 knockdown and enhanced by MTSS1 overexpression." (PMID 36810288, 2023). "Mtss1 plays an important role in metastasis blocking, by governing the metastatic nature of cancer cells, and its up-regulation was led by the CGA and STL diets." (PMID 35267932, 2022). "Genetic alterations in MIM/MTSS1 gene were found in 6% of sequenced cancer samples and, depending on the cancer type, both diminished or increased gene expression profiles are seen." (PMID 32373113, 2020). "As CK1δ regulates several mediators of cancer metastasis, such as wnt/β-catenin and metastasis suppressor 1 (MTSS1), we examined the effects of 13i HCl on migration by wound-healing assay." (PMID 32282334, 2020). "Studies demonstrated that the MTSS1 level reduced in numerous types of cancer and inhibited the migration and invasion of different cancer cells 23-25." (PMID 32929338, 2020). "Metastasis suppressor-1 (MTSS1) was originally identified as a metastasis suppressor in the carcinoma cell line." (PMID 33060738, 2020). "Our searches on cBioPortal, which contains over 200 deep-sequenced cancer datasets, also revealed that MTSS1 is altered in 6% of sequenced cancer patients (altered in 2983 of 49651 sequenced cases/patients)." (PMID 30858428, 2019). "Here, we mined protein expression databases TCGA and GTEx to gain a broader view on the MTSS1 gene expression levels of MIM in different cancers." (PMID 30858428, 2019). "Taken together, these observations highlight the cooperation of MTSS1 and Scamp1 in preventing HER2+/ER−/PR− cancer progression and provide further insights on early events associated with the pathogenesis of cancer invasion." (PMID 29497041, 2018). "Further studies are required to reveal the exact molecular mechanisms and signaling pathways through which MTSS1 modulates cancer cell migration and invasion." (PMID 24318128, 2013). "Among those targets, human MTSS1, known to have critical roles in the inhibition of cancer metastasis, contained two putative conserved miR-182 binding sites with high context scores." (PMID 22681717, 2012). "Metastasis suppressor 1 (MTSS1), one target gene of miR-182, plays an important role in the metastasis of cancers." (PMID 22681717, 2012). "Metastasis suppressor-1 (MTSS1) has been proposed to function as a cytoskeletal protein with a role in cancer metastasis." (PMID 21696600, 2011). "The results suggest an inhibitory effect on cell growth by MTSS1 over-expression in oesphageal cancer cells." (PMID 21696600, 2011). "This is due partly to the fact that the studies of MTSS1 have been restricted to a limited number of cancer types, with little support from the clinical aspect." (PMID 21696600, 2011). "Mtss1 is well-known to act as a tumor suppressor gene in different types of cancer since it controls cell proliferation, migration, invasion and metastasis of cancer cells by regulating actin dynamics and signalling pathways." (PMID 41288860, 2025). "The functions of MTSS1 in a variety of cellular processes must be better understood to understand this protein’s sentinel surveillance role in counteracting metastasis and possibly additional cancer hallmarks." (PMID 39625546, 2024). "Subsequently, MTSS1 was shown to be downregulated in many other types of cancers." (PMID 39625546, 2024). "MTSS1 protein levels in cancer cells can be reduced via proteasomal degradation." (PMID 39625546, 2024). "Concordantly, co-localization of MTSS1 with PD-L1 was observed in cancer cells." (PMID 36810288, 2023). "Concordantly, higher MTSS1 expression in cancer tissues correlated to improved patient survival." (PMID 36810288, 2023). "In addition, when cancer cells were co-cultured with Jurkat T cells, MTSS1 knockdown in H1975 significantly decreased IL-2 secretion from T cells." (PMID 36810288, 2023).
cancer (continued). "Moreover, the role of MTSS1 in plasma membrane protrusions, which stabilize epithelial junctions, suggests that in carcinoma cells expressing only low levels of MTSS1, the junctional integrity would be compromised." (PMID 36871754, 2023). "While MIM has been recurrently linked to various cancers, no disease-specific mutations have been identified to date in the MTSS1 gene." (PMID 30858428, 2019). "Expression of MTSS1 positively correlated with cancer survival (χ2 = 5.81, p = 0.016)." (PMID 29497041, 2018). "Importantly, co-expression of MTSS1 and SCAMP1 resulted in a more efficient inhibition of cell invasion and increased cell–cell adhesion in our cancer models when compared to the expression of Mtss1 or Scamp1 alone." (PMID 29497041, 2018). "Across the whole (unselected) population, MTSS1 expression did not associate with cancer-specific survival, but a relationship was detected with MTSS1 loss and metastasis development (χ2 = 3.83, p = 0.05)." (PMID 29497041, 2018). "Notably, the MTSS1 levels were higher in cancers at advanced stage than in early stage, in our study." (PMID 27230279, 2016). "Using the criteria of circadian proteomic expression, circadian expression in multiple tissues and independent gene knockdown data, we propose six genes (Por, Mtss1, Dgat2, Pim3, Ppp1r3b, Upp2) involved in metabolism and cancer for further experimental investigation." (PMID 26576534, 2015). "Currently, it remains unclear how MTSS1 is regulated in cancer cells, and whether reduced MTSS1 expression contributes to elevated cancer cell proliferation and migration." (PMID 24318128, 2013). "However, in contrast to its reduced expression in many human cancers, overpression of MTSS1 was observed in hepatocellular carcinoma although its physiological significance to liver cancer remains elusive." (PMID 24318128, 2013). "Therefore, our study provides a novel molecular mechanism for the negative regulation of MTSS1 by β-TRCP in cancer cells." (PMID 24318128, 2013). "However, it remains largely unclear how MTSS1 stability is physiologicaly controlled, and which upstream signaling pathway aberrantly activated in cancer cells, contributes to the reduced MTSS1 abundance frequently observed in various human cancers." (PMID 24318128, 2013). "the role of MTSS1 in cancer and cancer metastasis remains somewhat open." (PMID 21696600, 2011). "This indicates that MTSS1 serves as a potential prognostic indicator in human cancer." (PMID 21696600, 2011). "Inasmuch as the role of MTSS1 has not been clearly defined to date because of contradicting published data, we speculate that the role of MTSS1 could be cancer or tissue type specific." (PMID 20712855, 2010). "Moreover, MTSS1 reduced proliferation and invasiveness of cancer cell lines." (PMID 34029637, 2021). "A highly conserved, cancer-associated protein linked to the regulation of both the actin cytoskeleton and the plasma membrane, Missing in Metastasis (MIM) or Metastasis Suppressor 1 (MTSS1), is highly expressed in spleen and particularly in B cells (BioGPS.org and ImmGen.org portals)." (PMID 32373113, 2020). "Finally, to bring new understanding to the regulation of MTSS1 gene expression, highly significant both in cancer and in the tissue-specific physiological functions, we illustrate evolutionarily conserved transcriptional regulation with prediction of new transcription factor binding sites." (PMID 30858428, 2019). "However, the underlying molecular mechanisms responsible for reduced expression of MTSS1 in human cancers remain largely unknown." (PMID 24318128, 2013). "Restoration of MTSS1 function will be an interesting therapeutic approach for prevention of metastasis formation in NPC, and in other cancers." (PMID 37920825, 2023). "Correspondingly, experimental downregulation of MTSS1 in human AML cell lines increased their resistance to araC, DNR, and several other anti-cancer drugs." (PMID 33782537, 2021).